PIK3CA (phosphatidylinositol-4,5-bisphosphate 3-kinase catalytic subunit alpha)
Diseases named in the same sentence as PIK3CA in open-access papers (continued):
Sharing a sentence is not in itself a finding about the gene and the disease.
colon carcinoma (continued). "MEK inhibition led to a decrease in β-catenin in PIK3CA wt colon cancer cells but not in mt." (PMID 30944457, 2019). "In addition, our current cancer cell panel was limited to immortalized colon cancer cell lines due to the lack of reasonable PIK3CA-mutant and PIK3CA-wild-type rectal cancer cell line pairs in the American Type Culture Collection (ATCC)." (PMID 29152088, 2017). "Furthermore, molecular docking results indicated the stable binding connections between TQ/5-FU and the hub targets, i.e., MAP2K2, CASP3, PIK3CA, ESR1, CYP3A4, CYP2C19, and CYP2C9, suggesting that TQ, in combination with 5-FU, may treat colon cancer by modulating these hub targets." (PMID 39334689, 2024). "Furthermore, the current results indicate a role of mutations in KRAS, PIK3CA, and/or BRAF, and/or MMR deficiency in the etiological pathway between physical inactivity and colon cancer risk in women, but not men, and it seems that in particular PIK3CA mutations are involved in this association." (PMID 35546360, 2022). "Another large population-based study in colon cancer suggested that the activation of the PI3K/AKT or the RAS-RAF-MAPK pathway by mutation of at least one of the three genes predicted poor patient outcome, but the effect of mutations in PIK3CA alone was not discussed." (PMID 23617638, 2013). "Wild-type PIK3CA colon cancer cells displayed sensitivity to each of the MEK inhibitors; however, the mutant PIK3CA colon cancer cells did not respond to the MEK inhibitors." (PMID 30944457, 2019).
gastric cancer (181 papers, 2005 to 2026). A primary or metastatic malignant neoplasm involving the stomach. "EBV-positive gastric cancer is characterized by PD-L1/PD-L2 amplification and PIK3CA mutations, making it potentially sensitive to immunotherapy." (PMID 41361128, 2025). "As compared with 3–42% mutation frequency observed in other gastric carcinoma subtypes, PIK3CA mutations are present in >80% of EBVaGC, suggesting important oncogenic driver roles." (PMID 41315365, 2025). "PIK3CA mutations have been detected in gastric cancer, albeit at a lower frequency than breast and hepatocellular carcinomas." (PMID 38675376, 2024). "In contrast, the gene encoding for the alpha catalytic sub-unit of kinase PI3K, PIK3CA, was more frequently mutated in gastric cancers with lower expression of CDX2 (29% versus 16% in cancers with higher CDX2, Fisher’s exact test p = 0.02)." (PMID 39768557, 2024). "The two gastric carcinoma cases showed an ERBB2 R678Q pathogenic variant with a PIK3CA E542K and KRAS G12V variants." (PMID 36125633, 2023). "Another study identified the role of MSI status in mutations of exons 9 and 20 of the PIK3CA gene in gastric cancers." (PMID 35242279, 2022). "Conversely, in five of these genes, all clonally mutated patients had mutations that were likely pathogenic (CTNNB1, ELF3, ATM, KMT2E, and PIK3CA), lending stronger support to their candidate gastric cancer driver status." (PMID 36970058, 2022). "The PIK3CA activation mutations are the indication for the PIK3CA inhibitor regimen for advanced or metastatic breast cancer, but their efficacy on PIK3CA-mutated gastric cancer is still under investigation." (PMID 36612265, 2022). "Epstein–Barr virus-associated gastric cancer (EBVaGC) was one of four classifications of GC, with frequent mutations of PIK3CA, ARID1A, and BCOR, and PD-L1 and PD-L2 amplification; it accounts for up to 10% of its molecular subtypes." (PMID 36353623, 2022). "EBV-positive gastric cancers are reported to have recurrent mutations of PIK3CA, ARID1A, and BCOR and amplifications of JAK2, PD-L1, and PD-L224." (PMID 34873204, 2021). "Analysis of concurrent alterations in EBV positive gastric cancer (i.e., PIK3CA mutations, HER2 amplification) appear promising to identify mechanisms of resistance towards immunotherapy or to propose novel combinations." (PMID 34680363, 2021). "Gastric cancer with PIK3CA p.E545K and p.H1047R mutations were prominently enriched in the high-TMEscore group." (PMID 34376552, 2021). "Some mutations have been also observed in gastric cancer patients as well as Epstein-Barr virus infection including PIK3CA, ARID1A and BCOR mutations." (PMID 33024525, 2020). "Other genes that were commonly mutated in AN gastric cancer patients were PIK3CA, PTEN, KRAS, APC, and CTNN1B, which were comparable to the TCGA study." (PMID 31941061, 2020). "In our data analysis from the TCGA database, we found that PIK3CA has a mutation rate of 22.49% and that it ranks in the top 20 of all mutated genes in gastric cancer." (PMID 32596290, 2020). "Program death-ligand 1 (PD-L1) was expressed in 14% of AN patients who were more likely to have MMR deficiency, EBV-associated gastric cancers, and mutations in the PIK3CA gene, all of which have been linked to clinical response to PD-1 inhibitors." (PMID 31941061, 2020). "Our findings were further corroborated by clinical data; PDC progeny from a gastric cancer patient with PIK3CA-E542K mutation exhibited profound response to AZD5363, marked by partial clinical response." (PMID 32070411, 2020). "We evaluated the effect of PIK3CA codon 1047 mutations on patients’ survival after the surgical resection of gastric cancer." (PMID 29704890, 2019). "In gastric cancer, PIK3CA mutations are associated with a higher aggressiveness, while for the lymphomas a strong correlation with PTEN mutations is described." (PMID 31581674, 2019).
gastric cancer (continued). "Few studies have assessed the frequency of PIK3CA gene mutations in gastric cancer patients and their influence on patients’ survival." (PMID 29704890, 2019). "As reported, PIK3CA mutation frequency in gastric cancer is associated with cancer stage and Epstein–Barr virus (EBV) infection." (PMID 30754640, 2019). "In the present study, we demonstrated the presence of activating mutations in a single codon of PIK3CA gene in a significant number of Iranian patients with gastric cancer." (PMID 29704890, 2019). "The same is also true for PIK3CA H1047R mutations in stomach cancer, wherein MMR-associated processes increase the likelihood of the driver mutation, which is then subsequently strongly selected." (PMID 29748584, 2018). "Hotspot mutations of PIK3CA in exon 9 and exon 20 are known to be oncogenic in various tumor types, including esophageal, colorectal, brain, and gastric cancers." (PMID 30115035, 2018). "In conclusion, PIK3CA mutations were associated with increased tumor aggressiveness, especially in locoregional disease, and Akt activation in gastric cancer." (PMID 29207615, 2017). "In conclusion, mutations in PIK3CA exons 9 and 20 were observed in 25 of the 208 (12 %) gastric cancer patients by pyrosequencing assays." (PMID 27388016, 2016). "One of our novel findings is that PIK3CA amplifications were associated with more peritoneal recurrences of gastric cancers." (PMID 26701847, 2016). "Nevertheless, our cohort is the largest to date in which the clinicpathological characteristics and recurrence patterns regarding mutations in PI3K/AKT pathway genes and PIK3CA amplifications in gastric cancers were investigated." (PMID 26701847, 2016). "Mutations in genes involved in the PI3K/AKT pathway and amplifications of the PIK3CA gene in gastric cancer and their associations with clinicopathological characteristics and EBV infection were analyzed in this study." (PMID 26701847, 2016). "This study used pyrosequencing to evaluate PIK3CA mutations in patients with gastric cancer at our hospital, as well as determining the relationship between PIK3CA mutations and patient prognosis." (PMID 27388016, 2016). "In this study, the mutation rate of PIK3CA was 13.2% and that of PTEN was 4.0%, which is in accordance with the reported mutation rate of PIK3CA in gastric cancer but is lower than the mutation rates (18.75%) observed for PTEN in the study of Wen et." (PMID 26701847, 2016). "As previously reported, EBV-infected gastric cancer was associated with PIK3CA mutation, particularly those occurring in the body of the stomach." (PMID 26701847, 2016). "An inverse correlation between PIK3CA mutations and PIK3CA amplifications was reported in various cancers, including gastric cancer." (PMID 26701847, 2016). "This retrospective study investigated the relationship between PIK3CA mutations and clinical outcomes in patients with gastric cancer." (PMID 27388016, 2016). "This study examined the prognostic impact of PIK3CA mutations on survival in patients with gastric cancer." (PMID 27388016, 2016). "In their study, only PIK3CA mutations (rather than PI3K/AKT pathway mutations) were examined, and the incidence of PIK3CA mutations in gastric cancer patients was only 9 of 163 patients (5.5%)." (PMID 26701847, 2016). "We assessed the influence of PIK3CA mutations on clinical outcome in patients with curatively resected gastric cancer." (PMID 27388016, 2016). "Of the 208 patients who had undergone curative resection of gastric cancer, 25 (12 %) were found pyrosequencing technology to have PIK3CA exon 9 and 20 mutations." (PMID 27388016, 2016). "The previous study demonstrated that EBV-infected gastric cancer was associated with PIK3CA mutation, particularly those occurring in the body of the stomach, which was similar to our findings." (PMID 26701847, 2016).
gastric cancer (continued). "A salient feature of EBV-positive gastric cancer is PIK3CA mutation, which is found in 80% of such cancers compared with only 3–42% for cancers in the other three molecular classes." (PMID 25613731, 2015). "In gastric cancer, the PIK3CA mutation is an important biomarker for predicting the treatment response of everolimus and AKT inhibitors." (PMID 26267324, 2015). "For example, BRAF, KRAS, and PIK3CA, a set of rarely identified mutations in sporadic gastric cancers, have recently been reported in the microsatellite subsets of cancer." (PMID 25025766, 2014). "PIK3CA is an oncogene in various cancers, and thus it is one of the most genetically mutated genes in human cancers, including colorectal, brain and gastric cancers." (PMID 25054828, 2014). "The effect of the Akt inhibitor, AZD5363, was determined according to the mutation of PIK3CA in gastric carcinoma cells." (PMID 25003395, 2014). "In contrast, another study showed that PIK3CA mutations are rare, but their amplification is very common in gastric carcinoma." (PMID 25003395, 2014). "The catalytic subunit PIK3CA gene is mutated at a high frequency in gastric carcinoma cell lines and tumor tissues." (PMID 25003395, 2014). "Approximately 10% of gastric cancer patients carry a PIK3CA mutation, 20% a KRAS mutation and <2.7% a BRAF mutation." (PMID 24042258, 2013). "Using direct sequencing and real-time quantitative PCR, we examined PIK3CA mutations and amplification, and their association with clinicopathological characteristics and clinical outcome of gastric cancer patients." (PMID 22292935, 2012). "In the present study, a high prevalence of PIK3CA amplification was found in gastric cancer, which was significantly associated with poor prognosis of gastric cancer patients." (PMID 22292935, 2012). "The treatment benefit from PIK3 inhibitor in PIK3CA mutated gastric cancer should be tested in clinical trials." (PMID 22723903, 2012). "The Kaplan-Meier estimator of the survivorship function was used to determine the effect of PIK3CA mutations and amplification on the survival of gastric cancer patients." (PMID 22292935, 2012). "In gastric cancer, genetic mutation/amplification of PIK3CA, AKT1 and KRAS, and loss of heterozygosity of PTEN have been recognized so far." (PMID 22159814, 2012). "PIK3CA mutations and amplification were found in 8/113 (7.1%) and 88/131 (67%) gastric cancer patients, respectively." (PMID 22292935, 2012). "Among several isoforms of the catalytic subunits, only the α-type, PIK3CA, has been shown to harbor oncogenic mutations in human cancer, including gastric cancer, implying an important role of PIK3CA mutations in gastric carcinogenesis." (PMID 22292935, 2012). "The gene for phosphoinositide-3-kinase α peptide (PIK3CA) is highly mutated in colon, brain and gastric cancers where apparent gain-of-function mutations confer increased activity for this lipid kinase." (PMID 21208444, 2011). "Phosphatidylinositol 3-kinase α peptide (PIK3CA) is highly mutated in colon, brain and gastric cancers where apparent gain-of-function mutations confer increased activity for this lipid kinase." (PMID 21208444, 2011). "We found a relatively high prevalence of PIK3CA somatic mutations further supporting the role of PIK3CA as a major oncogene in gastric cancer." (PMID 20398348, 2010). "The aim of this study was to characterize the mutational status of PIK3CA in a large series of gastric cancers in order to determine its prevalence with an adequate precision and to correlate it with clinical-pathological features." (PMID 20398348, 2010).
gastric cancer (continued). "The aim of this study was to assess the frequency and type of PIK3CA mutations in gastric carcinoma and compare them with their clinical pathological correlates." (PMID 20398348, 2010). "Based on these data, we initiated PIK3CA mutation screening in 94 human gastric cancers by direct sequencing of the gene regions in which 80% of all the known PIK3CA mutations were found." (PMID 15784156, 2005). "Alternatively, amplification of AKT1 has been reported in a single case of gastric cancer, and amplification of PIK3CA associated with elevated mRNA levels has been found in 36% of gastric cancer." (PMID 15784156, 2005). "Major screening in colorectal cancer (CRC) identified PIK3CA mutations in 74 out of 234 (32%) cases, while mutations were also noted in 3 out of 12 (25%) gastric cancers." (PMID 15784156, 2005). "Moreover, PIK3CA mutations are linked to distinct immune profiles in gastric cancer and can modulate tumor immunogenicity." (PMID 40257955, 2025). "Therefore, PIK3CA mutations have been observed in gastric cancer, albeit at a lower frequency than other cancer types." (PMID 38675376, 2024). "Some of these mutations were detected in early lesions of gastric cancer, suggesting that PIK3CA mutation may occur independently of the stage of the tumors." (PMID 38675376, 2024). "The incidence of PIK3CA mutations in gastric cancer has been reported to be around 6.5%." (PMID 38675376, 2024). "The PIK3CA gene has been identified as a promising biomarker in gastric cancer, and its overexpression or mutation status may guide targeted therapeutic approaches." (PMID 38675376, 2024). "PIK3CA indicated an increasing risk of death in gastric cancer patients." (PMID 35903675, 2022). "PIK3CA with mutations and amplification has been seen frequently in gastric cancer." (PMID 34135756, 2021). "Under the collaborative environment of the SOLVE-RD consortium, re-analysis of whole-exome sequencing data from unresolved gastric cancer cases (n = 83) identified a mosaic missense variant in PIK3CA in a 25-year-old female with diffuse gastric cancer (DGC) without familial history for cancer." (PMID 34075207, 2021). "By contrast, the phosphatidylinositol 3-kinase catalytic subunit alpha (PIK3CA) mutation (which also occurs at a low frequency) was present in 5.5% of the cases; moreover, it is known to be highly correlated with Epstein–Barr virus-related gastric cancer." (PMID 34884530, 2021). "The multi-step procedure of autophagy could also be targeted in many steps such asPI3K, in cases of PIK3CA mutation, which is reported in 40% of hypermutated gastric malignant tumors." (PMID 34947835, 2021). "Our work raises the possibility that PIK3CA mutations may also be a potential therapeutic target in AN gastric cancer." (PMID 31941061, 2020). "Furthermore, previous studies have shown that PIK3CA mutation is a key molecular determinant to AKT inhibition response in gastric cancer cell-lines." (PMID 32070411, 2020). "Moreover, in gastric cancer, it has been well-known that PD-L1+ tumors frequently have PIK3CA mutations, which are also strongly associated with MSI-high and EBV+ tumors, as we observed in our cohort." (PMID 31941061, 2020). "However, based on the differences in etiologic factors of gastric cancer and disparities in patients’ outcome in distinct ethnicities, it is important to assess the rate of PIK3CA gene mutations in each region in association with patients’ survival." (PMID 29704890, 2019). "Consequently, in the present study, we evaluated the mutation status of a single hotspot codon in PIK3CA gene in Iranian patients with gastric cancer." (PMID 29704890, 2019). "Our data suggest that PIK3CA-mutated gastric cancer is a distinct disease entity, which might need a different therapeutic approach." (PMID 29207615, 2017). "Other studies have reported PIK3CA mutations in 4–25 % of gastric cancers." (PMID 27388016, 2016).